DES (desmin)
Description:
Muscle-specific type III intermediate filament essential for proper muscular structure and function. Plays a crucial role in maintaining the structure of sarcomeres, inter-connecting the Z-disks and forming the myofibrils, linking them not only to the sarcolemmal cytoskeleton, but also to the nucleus and mitochondria, thus providing strength for the muscle fiber during activity. In adult striated muscle they form a fibrous network connecting myofibrils to each other and to the plasma membrane from the periphery of the Z-line structures. May act as a sarcomeric microtubule-anchoring protein: specifically associates with detyrosinated tubulin-alpha chains, leading to buckled microtubules and mechanical resistance to contraction. Required for nuclear membrane integrity, via anchoring at the cell tip and nuclear envelope, resulting in maintenance of microtubule-derived intracellular mechanical forces (By similarity). Contributes to the transcriptional regulation of the NKX2-5 gene in cardiac progenitor cells during a short period of cardiomyogenesis and in cardiac side population stem cells in the adult. Plays a role in maintaining an optimal conformation of nebulette (NEB) on heart muscle sarcomeres to bind and recruit cardiac alpha-actin (By similarity).
Synonyms: CMD1I; CSM1; CSM2; LGMD2R; CDCD3; LGMD1D; LGMD1E
Tractability: Antibody: UniProt places it where antibodies can reach, with high confidence; its Gene Ontology location is reachable by antibodies, with high confidence. PROTAC: UniProt records ubiquitination sites on it; ubiquitination databases record sites on it.
Gene: Protein-coding gene on chromosome 2 (219,417,474 to 219,426,739, forward strand). Ensembl gene ENSG00000175084.
Subcellular location: Cytoplasm, myofibril, sarcomere, Z line; Cytoplasm; Cell membrane, sarcolemma; Nucleus; Cell tip; Nucleus envelope
Subcellular location (Human Protein Atlas): Intermediate filaments
Pathways (Reactome):
Muscle contraction: Striated Muscle Contraction
Gene Ontology:
Molecular function: cytoskeletal protein binding; identical protein binding; protein binding; structural constituent of cytoskeleton
Biological process: intermediate filament organization; cytoskeleton organization; muscle contraction; nuclear envelope organization; regulation of heart contraction; skeletal muscle organ development
Cellular component: cardiac myofibril; cytoplasm; extracellular exosome; intercalated disc; intermediate filament cytoskeleton; sarcolemma; Z disc; cell tip; cell-cell junction; cytosol; intermediate filament; nuclear envelope; nucleus; contractile muscle fiber; cytoskeleton; fascia adherens; neuromuscular junction; supramolecular fiber
Genetic constraint (gnomAD): Loss-of-function variants: 31 observed, 51.68 expected, observed/expected ratio (o/e) 0.6, 90% interval 0.45 to 0.81. The upper end of that interval is the gene's LOEUF score, 0.81, which puts it in group 3 of 6, group 1 being the genes least tolerant of losing a copy. Missense variants: 557 observed, 581.49 expected, observed/expected ratio (o/e) 0.96, 90% interval 0.89 to 1.03. Synonymous variants: 245 observed, 230.08 expected, observed/expected ratio (o/e) 1.06, 90% interval 0.96 to 1.18.
Gene-disease validity (ClinGen):
ClinGen rates the evidence that DES causes each of these diseases.
dilated cardiomyopathy 1I (autosomal dominant): Definitive. Any familial isolated dilated cardiomyopathy in which the cause of the disease is a mutation in the DES gene.
arrhythmogenic right ventricular cardiomyopathy (autosomal dominant): Moderate.
Homologues: Orthologues: macaque DES (99% identical), pig DES (99% identical), rabbit DES (99% identical), rat Des (98% identical), chimpanzee DES (97% identical), mouse Des (97% identical), guinea pig DES (95% identical), dog DES (88% identical), tropical clawed frog des (82% identical), zebrafish desma (72% identical), zebrafish desmb (71% identical). Paralogues in human: VIM (61% identical), PRPH (58% identical), GFAP (52% identical), INA (44% identical), NEFL (43% identical), NEFM (39% identical), KRT8 (33% identical), KRT5 (31% identical), KRT75 (31% identical), KRT84 (30% identical), KRT6C (30% identical), KRT15 (30% identical), and 56 more.
Diseases named in the same sentence as DES in open-access papers:
DES is named in the same sentence as 397 diseases in open-access papers, as found by Europe PMC text mining. Sharing a sentence is not in itself a finding about the gene and the disease. The quoted sentences say what the papers report.
cardiomyopathy (123 papers, 2007 to 2025). A disease of the heart muscle or myocardium proper. "In these disorders, loss of physiologic desmin localization and consequently its function induces cardiomyopathy that mimics the pathology observed with experimental mouse ablation of the DES gene in mice, whereby these disorders are termed desminopathies." (PMID 39932799, 2025). "A recent study showed that the cardiomyopathy-associated desmin mutation, p.R127P, severely disrupts filament assembly, compromising the structural integrity of cardiomyocyte and contributing to increased cardiac morbidity and mortality." (PMID 41440879, 2025). "Desminopathies are a group of rare human myopathies and cardiomyopathies caused by pathogenic variants of the desmin gene." (PMID 40033788, 2025). "These genes are described for being important for cardiac function and related cardiomyopathies directly linked to gene defects/mutations or genetic variation within these genes (DES, DSP, GJA1)." (PMID 41275133, 2025). "The term “desminopathies” refers to a group of rare human myopathies and cardiomyopathies caused by pathogenic variants of the desmin gene (DES) on chromosome 2q35." (PMID 40033788, 2025). "These alterations in the mutant protein, combined with the established role of arginine 163 in its interaction with desmin, clarify its pathogenic mechanism in cardiomyopathy." (PMID 40658662, 2025). "Since the first description, a multitude of inherited and de novo desmin mutations have been described, causing a broad spectrum of familial and sporadic (cardio)myopathies." (PMID 40033788, 2025). "Desmin, an intermediate filament cytoskeletal protein, has been implicated in heart failure and many cardiomyopathies." (PMID 39590189, 2024). "When the desmin filaments then aggregate, they cause cellular dysfunction which in the heart manifests mostly as forms of cardiomyopathies both hypertrophic and restrictive, although hypertrophy is more commonly noted." (PMID 38474073, 2024). "As was noted in the D109 mutants, the cardiac pathology that is most often associated with CRYABR120G is the development of desmin-related cardiomyopathy." (PMID 38474073, 2024). "Cardiomyopathies underlie complex pathomechanisms and animal models only partially recapitulate the proliferated and modified tubulin signature and changes in desmin levels." (PMID 37644284, 2023). "Genetic mutations of the intermediate filaments lamin A/C and desmin are known contributors of cardiomyopathies and heart failure." (PMID 37498175, 2023). "Desmin-related myopathies are characterized by progressive, distal skeletal muscle weakness, cardiomyopathy, and cardiac conduction disease caused by mutations of Desmin." (PMID 37082475, 2023). "We therefore postulate that the cardiomyopathy associated with desmin deficiency should be conceptualized as combined structural and mitochondrial cardiomyopathy." (PMID 36233322, 2022). "Desmin knock-out cardiomyopathy is considered a ‘structural cardiomyopathy’ caused by deficiency in an essential component of the extrasarcomeric cytoskeleton." (PMID 36233322, 2022). "Our results indicate that this desmin region is a hot spot for pathogenic mutations, leading to skeletal myopathies or cardiomyopathies." (PMID 36497166, 2022). "Protein degeneration due to abnormal aggregation of desmin has been implicated in such muscle disorders as atrophy and cardiomyopathy." (PMID 36232565, 2022). "Desmin aggregation in cardiomyocytes is the most significant histopathological hallmark of desmin cardiomyopathies." (PMID 36158202, 2022). "Genetic variations and loss of desmin drive a variety of conditions, so-called desminopathies, which include desmin-related cardiomyopathy, conduction system-related atrial and ventricular arrhythmias, and sudden cardiac death." (PMID 36158202, 2022). "Desmin organization defects severely impact muscle formation and maintenance, causing myopathies or cardiomyopathies." (PMID 36453730, 2022).
cardiomyopathy (continued). "The present findings demonstrate that in a rat model of T2DM-induced cardiomyopathy, there is evidence of an association between damage of the cardiac contractile unit—sarcomere and desmin—and the iNOS/mTOR/TIMP-1/collagen axis of fibrosis." (PMID 35625721, 2022). "UPS impairment has also been demonstrated in cardiomyopathy caused by mutations in desmin or αB-crystallin (CryAB) leading to accumulation of desmin in skeletal and cardiac muscle." (PMID 36111332, 2022). "Desminopathies comprise a group of rare cardiomyopathies and myopathies caused by mutations of the human desmin gene (DES) on chromosome 2q35." (PMID 36233322, 2022). "In a recent study performed in LmnaH222P/H222P mice, which carry an EDMD2 mutation and feature cardiomyopathy and muscular dystrophy, desmin toxicity due to formation of cytoplasmic aggregates was clearly shown." (PMID 33923914, 2021). "In conclusion, accumulation of p62‐positive protein aggregates is homogeneously distributed in the myocardium independently of fibrosis distribution and associated with desmin and phospholamban cardiomyopathy." (PMID 33605084, 2021). "Research also links mutations in the desmin gene to cardiomyopathy in up to 50% and to cardiac conduction disease or arrythmia in nearly 60% of patients." (PMID 33875675, 2021). "Desmin phosphorylation cause disturbance of the cytoskeletal network, thus leading to loss of function of desmin linked to cardiomyocyte death and development of cardiomyopathy." (PMID 34226534, 2021). "In conclusion, accumulation of p62‐positive protein aggregates is homogeneously distributed in the myocardium independently of fibrosis distribution and strongly associated with desmin and phospholamban cardiomyopathy." (PMID 33605084, 2021). "Desmin is localized to Z-discs and desmosomes within intercalated discs in muscle cells, and an imbalance in Desmin levels is a major cause of cardiomyopathies." (PMID 34152269, 2021). "Of note overexpression of alphaB-crystallin in laminopathic mice featuring cardiomyopathy obtained amelioration of the cardiac phenotype, showing that even mutated lamins elicit mitochondrial dysfunction dependent on an altered desmin network." (PMID 33923914, 2021). "We aimed to describe the prevalence, phenotypic expression, and mitochondrial function of individuals with putative disease-causing desmin (DES) variants identified in patients with an unexplained etiology of cardiomyopathy." (PMID 32235386, 2020). "Mutations in the desmin gene have been linked to cardiomyopathy as well as to cardiac conduction diseases and to arrhythmia." (PMID 32584885, 2020). "Another example of toxic protein aggregates and aggregate-prone desmin was uncovered in studies with modeling the cardiomyopathy-causing mutation H222P in the lamin A/C gene." (PMID 32581848, 2020). "Mutations of the human desmin gene on chromosome 2q35 cause a wide variety of hereditary and sporadic myopathies and cardiomyopathies." (PMID 33192292, 2020). "While deficiency of desmin is associated with cardiomyopathy and myocyte destruction, high levels of desmin or disorganization of desmin filaments have been found in cardiac hypertrophy and heart failure." (PMID 33139745, 2020). "The hallmark of desmin-related cardiomyopathy is the formation of aggregates consisting of desmin, an intermediate filament, and other proteins such as the small heat shock protein α-B-crystallin." (PMID 31361162, 2019). "Mutations in the human desmin gene cause autosomal-dominant and recessive cardiomyopathies and myopathies with marked phenotypic variability." (PMID 32322014, 2019). "Mutations in DES, encoding the muscle specific intermediate filament protein desmin, can cause myopathies, as well as different cardiomyopathies." (PMID 31718026, 2019).
cardiomyopathy (continued). "Mutations of the human desmin (DES) gene on chromosome 2q35, which encodes the muscle-specific intermediate filament protein desmin, cause autosomal-dominant and autosomal-recessive forms of cardiomyopathies and myopathies." (PMID 32322014, 2019). "For instance, disrupting the interaction between MTM1 and its intermediate filament, desmin, causes the formation of desmin aggregates, and this impairment is associated with myofibrillar myopathies and cardiomyopathies." (PMID 31245297, 2019). "One model of desmin-related cardiomyopathy caused by a missense mutation in the αB-crystallin (CryABR120G) is characterized by increased amyloid and aggregate formation as well as attenuated macroautophagy in the failing heart." (PMID 29576856, 2018). "Mutations in the small heat shock protein chaperone CRYAB (αB-crystallin/HSPB5) and the intermediate filament protein desmin, phenocopy each other causing cardiomyopathies." (PMID 28470624, 2017). "The desmin network’s pivotal role in myocytes is evident since mutations in the human desmin gene cause severe myopathies and cardiomyopathies." (PMID 28469177, 2017). "We showed that CVB3 infection causes a pathological phenotype similar to desmin-related cardiomyopathy." (PMID 29088822, 2017). "Collectively, our results suggest that CVB3 infection causes a pathological phenotype similar to desmin-related cardiomyopathy." (PMID 29088822, 2017). "Subsequently, mutations in both CRYAB and the muscle-specific IF protein desmin were found to phenocopy each other, causing cardiomyopathy." (PMID 28470624, 2017). "Since the first description of human desmin mutations in 1998, more than 70 myopathy- or cardiomyopathy-causing desmin mutations have been reported." (PMID 27393313, 2016). "Mutations of the human desmin gene on chromosome 2q35 cause autosomal dominant, autosomal recessive and sporadic forms of protein aggregation myopathies and cardiomyopathies." (PMID 25394388, 2015). "Mutations in the gene coding for desmin (DES) cause skeletal myopathies often combined with cardiomyopathy, or isolated cardiomyopathies." (PMID 25541946, 2014). "Mutations of the human desmin gene on chromosome 2q35 cause autosomal dominant, autosomal recessive, and sporadic myopathies and/or cardiomyopathies with marked phenotypic variability." (PMID 23143191, 2013). "This αB-crystallin mutant had previously been shown to cause a cardiomyopathy characterized by desmin-positive protein aggregates in heterozygous humans and transgenic mice." (PMID 23143191, 2013). "Studies of mice expressing DesI451M specifically in cardiac tissue have implicated this desmin mutant in cardiomyopathy onset." (PMID 24098483, 2013). "Mutations in DES disrupt the normal desmin intermediate filament networks and are known to cause a form of myofibrillar myopathy with a limb-girdle phenotype and/or cardiomyopathy." (PMID 23155419, 2012). "This became apparent when it was discovered that mutations in both αB-crystallin (R120G;) and desmin can cause cardiomyopathy, typified by aggregates containing both proteins." (PMID 22096479, 2011). "Transgenic (TG) mice with overexpression of an arg120gly (R120G) missense mutation in HSPB5 display desmin-related cardiomyopathy, which is characterized by formation of aggresomes." (PMID 21541347, 2011). "Cardiomyopathy has been reported in up to 50% of desmin gene mutation carriers, with DCM and RCM being the most prevalent form, but HCM has seldom been reported." (PMID 21083940, 2010). "Mutations in the desmin gene cause skeletal myopathies and cardiomyopathies." (PMID 41165044, 2025). "Furthermore, a comparable pattern of cytoplasmic pathology has been documented in a variety of other cardiac conditions including cardiomyopathies resulting from genetic mutations in desmin and junctional proteins." (PMID 40658643, 2025).